IL6 (interleukin 6)
Diseases named in the same sentence as IL6 in open-access papers (continued):
Sharing a sentence is not in itself a finding about the gene and the disease.
Hyperglycemia (continued). "This may be related to the continuous activation of cytokines such as interleukin-1 (IL-1), interleukin-6 (IL-6), and tumor necrosis factor-α (TNF-α) in diabetic patients, and the fact that hyperglycemia is associated with ROS production, leading to oxidative stress." (PMID 40783688, 2025). "Furthermore, hyperglycemia induces a pro-inflammatory microenvironment characterized by elevated levels of systemic markers such as IL-6 and TNF-α, which correlate with disrupted bone turnover and increased skeletal fragility through mechanisms distinct from direct glucose-mediated effects." (PMID 40276745, 2025). "Among the various inflammatory mediators, IL-6 and TNF-α have demonstrated consistent associations with early pregnancy glycemic alterations and have shown promise as predictive biomarkers of GDM prior to the onset of hyperglycemia detectable by oral glucose tolerance testing." (PMID 40722699, 2025). "The evidence showed hyperglycemia to be associated with unfavorable treatment outcomes; altered counts and functioning of dendritic cells, monocytes, and CD4+ T cells; and changes in cytokine levels (mainly INF-γ, IL-17, IL-1β, IL-2, IL-6, IL-10, and TNF-α) in patients with DM-TB." (PMID 39981106, 2024). "Granular UEA I staining was also observed with IL-6 treatment, which might indicate that IL-6 is the causative factor for glycocalyx damage in the diabetic cocktail, since hyperglycemia or TNF-α treatments alone did not alter UEA I." (PMID 38355716, 2024). "Moreover, it has been suggested that hyperglycemia may decrease cytokine production, such as IL-2, IL-6, and IL-10, impair leukocyte function, and impair leukocyte defense against infection." (PMID 39744260, 2024). "It should be noted that hyperglycemia was also linked to an increased risk of infection in vitro and after surgical procedures, which is due to the excessive release of proinflammatory cytokines, such as tumor necrosis factor-α (TNF-α), interleukin-1 (IL-1) and interleukin-6 (IL-6)." (PMID 35273985, 2022). "Hyperglycaemia, which is the earliest onset due to MetS, has a direct relationship with the development of inflammatory conditions by expressing pro-inflammatory cytokines like interleukin-6 (IL-6), tumor necrotizing factor-α (TNFα), and necrotizing factor (NF)." (PMID 35377899, 2022). "Chronic exposure to pro-inflammatory cytokines such as TNF-α, IL-1β and IL-6 activates the signaling proteins that block the activation of the insulin signaling cascade in the target organs of insulin, including skeletal muscle, adipose tissue and liver, leading to hyperglycemia." (PMID 34201653, 2021). "Hyperglycemia can induce nonenzymatic protein glycation, and the resulting advanced glycation end products (AGEs) have been shown to stimulate macrophages, causing them to release cytokines such as IL-6 and TNF-α, as well as C-reactive protein." (PMID 34068221, 2021). "Additionally, interleukin-6 and D-dimer levels were reduced after treating the hyperglycaemia." (PMID 33063540, 2021). "Finally, individuals with hyperglycemia were found to have higher levels of inflammatory cytokines such as interleukin-6 and tumor necrosis factor-alpha and these inflammatory factors may also have some adverse effects on muscle mass." (PMID 33046005, 2020). "In our study, the NFkB/pNFkB ratio increased in hyperglycemia compared to normoglycemia, suggesting the activation of the NFkB transcription factor in hyperglycemic conditions, in correlation with the increase of oxidative stress and inflammatory markers, especially IL-6, IL-31 and IL-33." (PMID 32824505, 2020). "Hyperglycaemia, alone can trigger inflammation by activating the pro-inflammatory transcription factor nuclear κB (NF-κB), resulting in an increased inflammatory chemokine and cytokine release including interleukin-6 (IL-6), interleukin-8 (IL-8), and tumor necrosis factor-α (TNF-α), among others." (PMID 32517031, 2020).
Hyperglycemia (continued). "It is also possible that hyperglycemia-induced oxidative stress could participate in this event, since sugar-derived substances called advanced glycation end products (AGEs) have been reported to stimulate IL6 production in human monocytes." (PMID 30513672, 2018). "Also, while our in vitro data explored the inhibition of IL‐6 during of acute hyperglycemia, our in vivo RNA‐seq data from the glucose‐octreotide protocol suggest that multiple other immune transcripts increase with hyperglycemia including IL‐12A, which is important in TH1 development." (PMID 27042306, 2016). "In a previous study, hyperglycemia over the level of 315 mg/dL could directly impair the functions of activated macrophages, resulting in up-regulation of the mRNA expressions of IL-1β and IL-6." (PMID 26207186, 2015). "Hyperglycemia stimulates the production of reactive oxygen species (ROS) and activates NF-κB, leading to the release of TNF-α and IL-6, perpetuating vascular dysfunction." (PMID 41993770, 2026). "For instance, transient hyperglycemia can induce adaptive responses such as increased production of antioxidants (e.g., glutathione) or upregulation of anti-inflammatory cytokines like IL-10, which may temporarily suppress pro-inflammatory mediators like IL-6 and IL-8." (PMID 41126323, 2025). "Long-term exposure to high-fat diets or hyperglycemia can impair endothelial cell function via inflammatory cytokines such as TNF-α, IL-1β, IL-6, and MCP-1." (PMID 40276785, 2025). "Consistent with previous reports, systemic improvements in hyperglycemia, insulin sensitivity, and reductions in peripheral inflammatory cytokines (e.g., TNF-α, IL-6) were observed in MSC-treated DM models." (PMID 40244194, 2025). "Conversely, IL-6 treatment increased SGLT2 expression in human kidney HK2 cells, suggesting a role for cytokines in the effects of hyperglycaemia." (PMID 40542280, 2025). "When the CC genotype (-174G/C IL6) is combined with the GA + 219A/T genotype in the ADIPOR2 gene, hyperglycemia is 1.3 times more frequent than with other IL6/ADIPOR2 genotype combinations." (PMID 41010061, 2025). "We demonstrated that hyperglycemia increased the production of TNF and IL-6 by LPS-stimulated bone marrow-derived macrophages (BMDMs) and peritoneal macrophages." (PMID 41244562, 2025). "In cell-based and organ-on-a-chip models, preeclampsia, infection, or hyperglycemia can be mimicked by inducing hypoxia, adding pro-inflammatory cytokines (such as TNF-α or IL-6), or applying high-glucose culture conditions." (PMID 41221050, 2025). "Studies have shown that hyperglycemia activated the production of inflammatory cytokines such as TNF, IL6, and IL1B, which contribute to kidney damage." (PMID 39911324, 2025). "Unlike diabetic patients, they may mount a more pronounced inflammatory response during acute hyperglycemia—a phenomenon observed in conditions such as acute myocardial infarction and trauma, where non-diabetic individuals consistently exhibited higher levels of inflammatory cytokines (e.g., IL-6)." (PMID 40309818, 2025). "Conversely, hyperglycemia and pro-inflammatory cytokines, such as TNF-α, IL-1, and IL-6, upregulate iNOS expression, resulting in excessive and sustained NO production." (PMID 41011276, 2025). "Hyperglycemia stimulates the production of proinflammatory cytokines, including tumour necrosis factor‐alpha (TNF‐α), interleukins (IL‐1, IL‐6, IL‐12), adhesion molecules, and dendritic cells." (PMID 40931439, 2025). "Hyperglycemia and adipose tissue create a low-grade inflammatory state, increasing pro-inflammatory factors (e.g., TNF-α, IL-1β, IL-6) and ECM degradation." (PMID 41158135, 2025). "Traumatic injury triggers substantial release of pro-inflammatory cytokines (IL-6, TNF-α, IL-1β) that induce stress hyperglycemia, which subsequently enhances neuronal excitability through glutamate-mediated mechanisms." (PMID 40303892, 2025).
Hyperglycemia (continued). "Inflammatory factors, such as IL-6, TNF-α, cleaved caspase-1, and pro-IL-1β are downstream of the NF-κB signaling pathway and are also involved in neuroinflammation induced by hyperglycemia." (PMID 38421831, 2024). "During inflammatory responses, hyperglycemia and oxidative stress induce PTECs to release large amounts of pro-inflammatory factors such as TNF-α and IL-6." (PMID 39795078, 2024). "Hyperglycemia was also shown to enhance SARS-CoV-2 replication and the production of proinflammatory cytokines such as TNF-α and IL-6 in monocytes in vitro." (PMID 37934800, 2024). "IL-6 also activates suppressor of cytokine signaling (SOCS) proteins, which inhibit insulin signaling and glucose uptake, worsening hyperglycemia." (PMID 39857603, 2024). "Another study also demonstrated that hyperglycemia induced the protein expression of COX-2 and the production of PGE2, IL-6 and MMP-13, and concomitantly decreased the protein expression of type 2 collagen in human chondrocytes." (PMID 38339087, 2024). "In the presence of hyperglycemia, the proinflammatory cytokines (TNF-α, growth factors, IL-1, IL-6) increase and are believed to be involved in the initiation and exacerbation of inflammation in DR." (PMID 38540165, 2024). "The decreased secretion of anti-inflammatory adiponectin and the increased secretion of pro-inflammatory leptin and IL-6 is reported in GDM, similar to high concentrations of TNF-α and IL-1β due to hyperglycaemia." (PMID 37627482, 2023). "In patients with hyperglycemia, researchers have detected chronic low-grade, subclinical inflammation mediated by TNF-α, COX-2, IL-1β, IL-6, and MCP-1, which is responsible for vascular complications." (PMID 36982499, 2023). "The byproducts of hyperglycaemia, AGEs, regulate inflammation by increasing NF-κB nuclear localisation and induction of IL-1β, TNF-α, macrophage inflammatory protein 2 (MIP2), IL-6 and IL-10." (PMID 37670018, 2023). "The U-shaped response of IL-6, the rise of FGF-21 during hyperglycemia and the hyperglycemia-induced suppression of VEGF-A are in keeping with previous studies." (PMID 37400734, 2023). "There is evidence that hyperglycemia increases the secretion of tumor necrosis factor alpha (TNF⁃α), interferon γ (IFN⁃γ), resistin, and interleukin-6 (IL-6), leading to tumor-related inflammation." (PMID 36672448, 2023). "Hyperglycemia promotes the production of proinflammatory cytokines TNF-α and IL-6 production, and the expression of these proinflammatory cytokines induces an increase in MMP9 expression in an autocrine and paracrine manner." (PMID 36820318, 2023). "In cultured macrophages, intermittent episodes of hypoglycemia and hyperglycemia promote M1 polarization and enhance IL-1β, TNF-α, IL-6, and MCP-1 secretion." (PMID 37893217, 2023). "In vitro investigations of adipocytes have revealed that oxidative stress induced by hyperglycemia can stimulate adipocytes to secrete LEP, MCP-1, and interleukin-6 (IL-6)." (PMID 37957155, 2023). "It has been shown that 6-gingerol has renoprotective effects in diabetic rats due to its ability to regulate urea and creatinine levels, inhibiting oxidative stress, hyperglycemia, and inflammatory markers such as CRP, IL-6, IL-1, and TNF-α." (PMID 36557312, 2022). "None of the SGLT-2i tested was able to hamper the increase in the mRNA expression of IL-6, IL-8 and IL-1β induced by LPS in THP-1 or by hyperglycaemia in HUVEC, suggesting that these drugs do not have intrinsic anti-inflammatory properties in these settings." (PMID 35503137, 2022). "In obese diabetic ob/ob mice, COS supplementation improved BW gain, dyslipidemia, and hyperglycemia, as well as regulated a variety of adipokine expression, shown by an increase in adiponectin and a decrease in RBP4, resistin, TNF-α, and IL-6." (PMID 36547931, 2022). "In response to hyperglycemia, AGER is activated by S100A8/A9 on hepatic Kupffer cells, leading to the secretion of IL-6." (PMID 35330392, 2022).
Hyperglycemia (continued). "In vitro studies in cytotrophoblast cells show that hyperglycemia-induced states down-regulate angiogenic factors (VEGF, PlGF) and stimulate apoptosis, antiangiogenesis, and inflammation (higher sFlt-1, sEng, and IL-6 levels)." (PMID 35631313, 2022). "Both T2DM and new-onset hyperglycemia groups demonstrated higher levels of inflammatory markers, namely white blood cell counts (WBC), C-reactive protein (CRP), D-dimer, and interleukin-6, except for the plasma fibrinogen concentration." (PMID 35949446, 2022). "Consumption of calorie dense diet and high fat diet (HFD) produces elevation in the production of IL-6 and TNF-α that, in turn, aggravates hyperglycemia." (PMID 36778598, 2022). "T2DM is a low level chronic inflammatory disease, accompanied by elevated IL-6 and C-reactive protein (CPR), while chronic inflammation can build a bridge between hyperglycemia and cognitive impairment." (PMID 36310847, 2022). "In accordance with the ROS results, the TUNEL staining and IL-6/TNF-α results also showed that KDM3A knock-out evidently alleviated sustained apoptosis and inflammatory responses induced by hyperglycemia." (PMID 35571189, 2022). "Alternatively, hyperglycemia contributed to Kupffer cells activating and then secreting proinflammatory cytokines such as TNF-α and IL-6." (PMID 33809508, 2021). "Persistent hyperglycemia and excess FFA levels produce cytokines, including IL-6 and nuclear factor κB (NF-κB), which lead to chronic systemic inflammation." (PMID 34068776, 2021). "First of all, we analyzed mRNA levels of EMT and CSC inducers—namely, the cytokines IL-6, IL-8, TNF-α and TGFβ-1—in PDEC exposed to M1-polarized macrophages and/or hyperglycemia." (PMID 34064969, 2021). "Persistent hyperglycemia activates NF-κB, which increases the expression of various adhesion molecules and proinflammatory cytokines (i.e., ICAM-1, MCP-1, IL-1β, and IL-6)." (PMID 34281287, 2021). "DM and PD involve significant impairment of immune system regulation, while hyperglycemia contributes to advanced glycation end products (AGE) formation and extended levels of proinflammatory cytokines IL-1β, interleukin 6 (IL-6) and TNF-α." (PMID 32093297, 2020). "Furthermore, Hyperglycemia could also increase inflammatory cytokine (including tumor necrosis factor‐α [TNF‐α], interleukin‐6 [IL‐6], and interleukin‐18 [IL‐18]) by an oxidative stress mechanism in human, suggesting hyperglycemia triggers inflammatory response." (PMID 32697441, 2020). "Firstly, hyperglycemia in T2DM patients increases a variety of signaling pathways and upregulates the expression of inflammatory factors such as IL-6 and TNF-α." (PMID 33456672, 2020). "Older age, neutrophilia, thrombocytopenia, hyperglycemia and elevated LDH, serum creatinine, BUN, hs-cTnT, BNP, PCT, hsCRP, IL-6, IL-10, TNFα and poorly controlled hyperglycemia were also associated with death." (PMID 33382747, 2020). "Compared with healthy controls, an induced hyperglycemia in diabetic patients results in a more pronounced secretion of pro-inflammatory cytokines such as tumor necrosis factor-α (TNF-α) and IL-6." (PMID 32430795, 2020). "Oxidative stress resulting from hyperglycemia was confirmed to promote expression of inflammatory cytokines such as TNF-α and IL-6, and generation of ROS accelerates myocardial fibrosis via regulating inflammatory and apoptotic signaling." (PMID 32952955, 2020). "Hyperglycemia increased levels of inflammatory cytokines such as TNF-α and IL-6 in the serum of STZ-induced diabetic rats." (PMID 32952955, 2020). "BDNF also restores the morphology of activated microglia induced by hyperglycemia close to the resting state and suppresses the increased levels of TNF-α and IL-6." (PMID 31165005, 2019). "The impact of hypoxia and hyperglycemia on the gene expression of TNF- α, IL-1a, IL-6 and GM-CSF was analyzed in detail and compared to the results obtained with the microarray." (PMID 31415598, 2019).
Hyperglycemia (continued). "The role of inflammation was previously demonstrated in the development of T2DM and hyperglycemia was shown to increase the circulating TNF-α and IL-6." (PMID 31442295, 2019). "Hyperglycemia alone upregulates the expression of inflammatory cytokines such as TNF-α, IL-1, IL-6, and chemokines in monocytes, epithelial cells, and plasma." (PMID 31073533, 2019). "We have also previously reported that knockdown of CB1R signaling effectively attenuates the hyperglycemia-induced upregulation of c-Jun, TGF-β1, IL-6, and TNF-α in vitro and in vivo." (PMID 30642005, 2019). "Hyperglycemia upregulated the expression of pro-inflammatory cytokines such as TNF-α, IL-1, IL-6, chemokines and downregulated the expression of two receptors involved in phagocytosis (CD 36 and Class B scavenger type I receptors)." (PMID 31415598, 2019). "More interestingly, BDNF inhibited hyperglycemia-induced microglial activation and reduced elevated levels of inflammatory factors (TNF-α, IL-6)." (PMID 31165005, 2019). "This can translate into low TNF-α expression in POD2B/T2D patients because hyperglycemia can overregulate levels of TNF-α, and other cytokines such as GM-CSF and IL-6, in both healthy and periodontal affected tissues." (PMID 31355282, 2019). "After one hour post LPS activation, the combination of hypoxia and hyperglycemia had a dramatic effect on the expression of TNF-α and IL-6." (PMID 31415598, 2019). "The combination of hyperglycemia and hypoxia is required to induce a sustained production of pro-inflammatory cytokines as the same phenomenon was observed for TNF-α and IL-6." (PMID 31415598, 2019). "The results showed that hyperglycemia treatment (HG/VEH) significantly increased the secretion of IL1β, IL6, and MCP1 to 261%, 311%, and 156%, respectively, compared to the LG/EMP group." (PMID 31616304, 2019). "It is known that hyperglycemia increases the production of pro-inflammatory cytokines like TNF-α, IL-1β, and IL-6, which act by way of NF-kB." (PMID 29694627, 2018). "In obese animals, chokeberry suppressed visceral fat accumulation and hyperglycemia, elevated plasma adiponectin and inhibited the plasma TNF-α and IL6 levels." (PMID 29182628, 2017). "In a similar manner, curcumin exerted antioxidant effect, reducing hyperglycemia and also inhibited macrophages-mediated tumor necrosis factor (TNF) and interleukin-6 (IL-6) release, activated by dying or stressed B cells." (PMID 28194110, 2017). "Obese mice exhibited hyperglycemia (p < 0.05); increased levels of proinflammatory cytokines (MCP-1, IL-6, p < 0.05); oxidative stress (p < 0.05); and increased hepatic hepcidin levels (p < 0.05)." (PMID 29062571, 2017). "It is widely accepted that hyperglycemia stress, increases cytokines secretion such as TNF-α, IL-6 and IL-1β and alters gene expression profile in targeted cells." (PMID 27942499, 2016). "Hyperglycemia triggers chronic systemic inflammatory responses and induces the expression of a variety of inflammatory factors, including NFκB, TNF-α and IL-6, which also promote PC progression." (PMID 27413117, 2016). "In Müller cells exposed to hyperglycaemia, the protein levels of MCP-1, soluble ICAM-1, CCL20, growth-regulated oncogene/cytokine-induced neutrophil chemoattractant-1 (GRO/CINC-1), VEGF and IL-6 were increased compared to normoglycaemic controls." (PMID 26222724, 2015). "In contrast to studies using cell lines, hyperglycemia significantly decreased the respiratory burst of alveolar macrophages and impaired proinflammatory cytokine secretion, such as TNF-α and IL-6." (PMID 24899891, 2014). "The key markers of oxidative stress and inflammation such as inflammatory cytokines (IL-1β, IL-6, and TNF-α) and immunoregulatory cytokines (IL-4 and IFN-γ) were increased in kidneys along with significant hyperglycemia." (PMID 25295146, 2014).